MIR144 (microRNA 144)
Synonyms: hsa-mir-144; MIRN144; mir-144
Gene: MicroRNA gene on chromosome 17 (28,861,533 to 28,861,618, reverse strand). Ensembl gene ENSG00000283819.
Gene Ontology:
Biological process: miRNA-mediated post-transcriptional gene silencing
Cellular component: RISC complex
Homologues: Orthologues: macaque mml-mir-144 (99% identical), chimpanzee ptr-mir-144 (98% identical), rat Mir144 (92% identical), pig ssc-mir-144 (90% identical), guinea pig MIR144 (76% identical), mouse Mir144 (76% identical), zebrafish mir144 (74% identical), rabbit MIR144 (66% identical), dog MIR144 (65% identical), tropical clawed frog xtr-mir-144 (65% identical).
Diseases named in the same sentence as MIR144 in open-access papers:
MIR144 is named in the same sentence as 1 disease in open-access papers, as found by Europe PMC text mining. Sharing a sentence is not in itself a finding about the gene and the disease. The quoted sentences say what the papers report.
COVID-19 (1 paper, 2022). A disease caused by infection with severe acute respiratory syndrome coronavirus 2. "Notably, the lower expression of MIR144 is also observed, which is consistent with the differential expression analysis in the peripheral blood of COVID-19 patients." (PMID 35409008, 2022).